CADM1 (cell adhesion molecule 1)
Description:
Mediates homophilic cell-cell adhesion in a Ca(2+)- independent manner. Also mediates heterophilic cell-cell adhesion with CADM3 and NECTIN3 in a Ca(2+)- independent manner (By similarity). Interaction with CRTAM promotes natural killer (NK) cell cytotoxicity and interferon-gamma (IFN-gamma) secretion by CD8+ cells in vitro as well as NK cell-mediated rejection of tumors expressing CADM1 in vivo. In mast cells, may mediate attachment to and promote communication with nerves. CADM1, together with MITF, is essential for development and survival of mast cells in vivo. By interacting with CRTAM and thus promoting the adhesion between CD8+ T-cells and CD8+ dendritic cells, regulates the retention of activated CD8+ T-cell within the draining lymph node (By similarity). Required for the intestinal retention of intraepithelial CD4+ CD8+ T-cells and, to a lesser extent, intraepithelial and lamina propria CD8+ T-cells and CD4+ T-cells (By similarity). Interaction with CRTAM promotes the adhesion to gut-associated CD103+ dendritic cells, which may facilitate the expression of gut-homing and adhesion molecules on T-cells and the conversion of CD4+ T-cells into CD4+ CD8+ T-cells (By similarity). Acts as a synaptic cell adhesion molecule and plays a role in the formation of dendritic spines and in synapse assembly (By similarity). May be involved in neuronal migration, axon growth, pathfinding, and fasciculation on the axons of differentiating neurons (By similarity). May play diverse roles in the spermatogenesis including in the adhesion of spermatocytes and spermatids to Sertoli cells and for their normal differentiation into mature spermatozoa (By similarity). Acts as a tumor suppressor in non-small-cell lung cancer (NSCLC) cells. May contribute to the less invasive phenotypes of lepidic growth tumor cells. [Isoform 5]: (Microbial infection) Induces cell fusion in neuron infected by a neuropathogenic strain of measles. Interacts with measles hemagglutinin to trigger hyperfusogenic F-mediated membrane fusion and presumably transsynaptic cell-to-cell transmission of the virus.
Synonyms: IgSF4; NECL-2; SgIgSF; SynCAM; IGSF4A; NECL2; TSLC1; ST17; BL2; SYNCAM1; RA175; sTSLC-1
Tractability: Antibody: UniProt places it where antibodies can reach, with high confidence; its Gene Ontology location is reachable by antibodies, with high confidence; UniProt predicts a signal peptide or a membrane-spanning region; the Human Protein Atlas places it where antibodies can reach. PROTAC: ubiquitination databases record sites on it; its protein half-life has been measured.
Gene: Protein-coding gene on chromosome 11 (115,169,218 to 115,504,957, reverse strand). Ensembl gene ENSG00000182985.
Subcellular location: Cell membrane; Synapse
Subcellular location (Human Protein Atlas): Plasma membrane
Pathways (Reactome):
Cell-Cell communication: Adherens junctions interactions; Nectin/Necl trans heterodimerization
Gene Ontology:
Molecular function: identical protein binding; protein binding; signaling receptor binding; PDZ domain binding; protein homodimerization activity
Biological process: activated T cell proliferation; cell recognition; detection of stimulus; positive regulation of cytokine production; positive regulation of natural killer cell mediated cytotoxicity; susceptibility to natural killer cell mediated cytotoxicity; T cell mediated cytotoxicity; heterophilic cell-cell adhesion; homophilic cell-cell adhesion; lymphocyte migration into lymphoid organs; maintenance of postsynaptic specialization structure; presynapse assembly; retrograde trans-synaptic signaling by trans-synaptic protein complex; synaptic membrane adhesion
Cellular component: plasma membrane; basolateral plasma membrane; cell-cell junction; neuron projection; synapse; axon; dendrite; glutamatergic synapse; postsynaptic membrane; presynaptic membrane; Schaffer collateral - CA1 synapse; synaptic vesicle
Genetic constraint (gnomAD): Loss-of-function variants: 13 observed, 48.95 expected, observed/expected ratio (o/e) 0.27, 90% interval 0.17 to 0.42. The upper end of that interval is the gene's LOEUF score, 0.42, which puts it in group 1 of 6, group 1 being the genes least tolerant of losing a copy. Missense variants: 415 observed, 606.97 expected, observed/expected ratio (o/e) 0.68, 90% interval 0.63 to 0.74. Synonymous variants: 273 observed, 242.4 expected, observed/expected ratio (o/e) 1.13, 90% interval 1.02 to 1.25.
Homologues: Orthologues: chimpanzee CADM1 (99% identical), macaque CADM1 (99% identical), mouse Cadm1 (99% identical), guinea pig CADM1 (98% identical), rat Cadm1 (98% identical), pig CADM1 (95% identical), rabbit CADM1 (93% identical), dog CADM1 (75% identical), tropical clawed frog cadm1 (65% identical), zebrafish cadm1a (61% identical), zebrafish cadm1b (55% identical), Drosophila melanogaster Fas3 (18% identical). Paralogues in human: CADM2 (39% identical), CADM4 (34% identical), CADM3 (33% identical), NECTIN3 (20% identical), NECTIN2 (18% identical), NECTIN1 (18% identical), NECTIN4 (18% identical), PVR (18% identical), CRTAM (13% identical), CD226 (12% identical), CD200 (9% identical), TIGIT (8% identical), and 2 more.
Diseases named in the same sentence as CADM1 in open-access papers:
CADM1 is named in the same sentence as 192 diseases in open-access papers, as found by Europe PMC text mining. Sharing a sentence is not in itself a finding about the gene and the disease. The quoted sentences say what the papers report.
cervical cancer (35 papers, 2005 to 2025). A primary or metastatic malignant neoplasm involving the cervix. "In conclusion, we demonstrated that the inactivation of CADM1 was associated with its hypermethylation in HPV-induced cervical cancer." (PMID 25845528, 2015). "The detection of CADM1 promoter methylation in cervical cancer cell lines is in concordance with our previous study showing reduced CADM1 mRNA expression associated with promoter methylation in nearly all cervical cancer cell lines, and not in HPV-immortalised cells." (PMID 17971771, 2007). "The integration of highly sensitive platforms like ddPCR and validated gene panels such as CADM1/MAL represents a promising direction in the development of molecular strategies for cervical cancer triage, particularly among HPV-positive women." (PMID 40564169, 2025). "PAX1, MAL, and CADM1 have been proposed as tumour suppressor genes involved in the development and progression of cervical cancer." (PMID 40564169, 2025). "More studies suggest that CADM1 is involved in the occurrence of cervical cancer, breast cancer, and liver cancer." (PMID 35845138, 2022). "Here, we established a liquid biopsy-based assay to detect MAL and CADM1 methylation in cell free DNA of cervical cancer." (PMID 36010947, 2022). "In cfDNA samples of 24 cervical cancer patients, CADM1/MAL methylation was detected in 83.3% of the cases." (PMID 36010947, 2022). "Methylation analyses of cervical cancer tissue have shown that cell adhesion molecule 1 (CADM1) and myelin and lymphocyte protein (MAL) methylation are present in over 90% of all cervical high-grade neoplasias and invasive cervical cancers." (PMID 36010947, 2022). "ROC analysis for CADM1/MAL as a combined marker resulted in a significant area under the curve (AUC) of 0.872 (95% confidence interval: 0.743–1.000) for differentiation of cervical cancer patients and healthy donors." (PMID 36010947, 2022). "Methylation analyses of cervical cancer tissue have shown that CADM1/MAL methylations are present in up to 99% of all squamous cell carcinomas and 92% of all adenocarcinomas." (PMID 36010947, 2022). "Our calculated sensitivity for CADM1 methylation in plasma alone for the detection of cervical cancer is 75%; the specificity to healthy controls is 100%." (PMID 36010947, 2022). "Exemplarily, follow-up samples were collected from three cervical cancer patients and tested for CADM1 and MAL methylation." (PMID 36010947, 2022). "Specifically, we characterized aberrantly methylated host promoter genes (RARB, CADM1, DAPK1, and PAX1) and their possible association with: invasive cervical cancer, cervical cancer stage, HIV status, age, high-risk HPV genotypes." (PMID 33718129, 2021). "The severity of cervical lesions is correlated with CADM1 promoter methylation, which suggests that it can be used as a new biomarker in the early diagnosis of cervical cancer." (PMID 34395444, 2021). "In vitro studies also demonstrated that miR-205 targets CADM1 and that downregulated miR-205 inhibits cervical cancer cell invasion and angiogenesis through the CADM1-mediated Akt signaling pathway, as validated by in vivo experiments in nude mice." (PMID 34395444, 2021). "Studies have shown that CADM1 expression is significantly low, and invasion, migration, and angiogenesis of cells in cervical cancer are high." (PMID 34395444, 2021). "HPV16 E7 infection of cervical cancer cell lines induces CADM1 promoter methylation, which inhibits the expression of CADM1." (PMID 34395444, 2021). "There was a significant difference in the promoter methylation of plasma CADM1 and its D-dimer between healthy individuals and those with cervical cancer." (PMID 32328088, 2020). "The usefulness of plasma CADM1 methylation as a metastasis biomarker in cervical cancer has been reported." (PMID 33419290, 2020).
cervical cancer (continued). "Methylation-mediated silencing of the CADM1 has been reported in cervical carcinoma cell line, advanced stage of cervical intraepithelial neoplasia (CIN) lesion and cervical squamous cell carcinoma (SCC) lesion in hrHPV-positive women." (PMID 30608989, 2019). "In this study, we explored the relationship between CADM1 methylation status and its expression in various cervical cancer cell lines." (PMID 25845528, 2015). "Based on our results, we suggest that CADM1 methylation is one of the common epigenetic alterations in HPV-infected cervical cancers." (PMID 25845528, 2015). "Treatment with 5-aza-dC increased CADM1 expression levels in three cervical carcinoma cell lines that lack the endogenous CADM1 protein, thus confirming that promoter methylation is involved in the silencing of CADM1 in cervical carcinoma." (PMID 25845528, 2015). "In contrast, the CADM1 mRNA was undetectable in three cervical carcinoma cell lines (i.e., HeLa, SiHa, and CaSki)." (PMID 25845528, 2015). "Application to an integrative oncogenomics study, involving HPV-transformed cell lines, confirmed genes CADM1 and SLC25A36, known to be implicated in the development of cervical cancer." (PMID 25278371, 2014). "Promoter methylation of the CADM1 gene has also been described in several other types of cancer, including nonsmall cell lung carcinoma, pancreatic cancers, and cervical carcinomas 27,47." (PMID 25065733, 2014). "In parallel to CADM1 we analysed MAL promoter methylation which was shown to be relevant in the viral oncogenesis of cervical cancer." (PMID 21535891, 2011). "Cervical carcinoma cell lines, showed next to markers present in FK cell lines, also revealed frequent methylation of CADM1 and CHFR." (PMID 17971771, 2007). "Methylation of CHFR, CDH13 and CADM1 was only observed in cervical carcinomas and cervical carcinoma cell lines and can as such be designated as relative late events." (PMID 17971771, 2007). "The frequency and density of CADM1 promoter methylation increases with high-grade precancerous lesions and cancer compared to normal tissue, and it ranges from 5% in normal tissue to more than 80% in cervical cancer lesions." (PMID 37047452, 2023). "For CADM1, one study in cfDNA in cervical cancer has been published." (PMID 36010947, 2022). "Moreover, cervical biopsy experiments suggested that the CADM1 promoter methylation rate in cervical cancer is higher than that in normal tissues and low-grade squamous intraepithelial lesion (LSIL) or CIN1." (PMID 34395444, 2021). "Plasma levels of methylated CADM1 are increased in patients with advanced cervical cancer." (PMID 33419290, 2020). "Concomitantly, we investigated whether CADM1 expression could be restored in cervical cancer cell lines expressing methylated CADM1 that were treated with the demethylation reagent 5-aza-2′-deoxycytidine (5-aza-dC)." (PMID 25845528, 2015). "CADM1 expression is frequently down-regulated and its promoter hypermethylated in many human cancers, including lung, prostate, pancreatic, gastric, breast, esophageal and uterine cervix cancer." (PMID 25774694, 2015). "However, to date, little is known about the role of the hypermethylation of CADM1 in cervical cancer." (PMID 25845528, 2015). "To explore whether HPV infection is related to CADM1 expression, we investigated the level of CADM1 in various cervical cancer cells, such as C33A (HPV-negative), HeLa (HPV18-positive), SiHa and CaSki (HPV16-positive) cells." (PMID 25845528, 2015). "Our results demonstrate that epigenetic alteration of CADM1 was more frequent in HPV-positive cervical cancers and that restoration of CADM1 expression may be a potential strategy for cervical cancer therapy." (PMID 25845528, 2015).
cervical cancer (continued). "Our study showed that the cell adhesion molecule 1 (CADM1) is downregulated in human papillomavirus (HPV)-infected cervical cancer cell lines via its hypermethylation and demethylation using 5-aza-2′-deoxycyticine (5-aza-dC) restored the expression of CADM1 protein." (PMID 25845528, 2015). "CADM1 gene silencing was significantly observed in HPV-induced cervical carcinoma cell lines." (PMID 25845528, 2015). "Although ample studies have demonstrated that CADM1 expression is silenced by promoter methylation in many solid tumors such as lung, melanoma, pancreatic, esophageal, uterine, and cervical cancer, its mechanistic functional roles as a tumor suppressor are unknown." (PMID 29698475, 2018). "Moreover, CADM1 hypermethylated cervical cancer cells were treated with the DNA methylation inhibitor 5-aza-dC to determine whether methylation of CADM1 was the reason for its silencing." (PMID 25845528, 2015). "In addition to the epidemiological studies of CADM1 in cervical cancer performed to date, the functional involvement of CADM1 in tumor suppression has been reported by very few studies and remains unclear." (PMID 25845528, 2015). "In a study with 79 cases, DNA methylation of CADM1, MAL, and miR124-2 in cervical scrapes had been shown to be present in all cervical cancer cases." (PMID 41008854, 2025). "The methylation pattern of CIN2 lesions was similar to CIN3 and cervical cancer for miR124 and MAL, but it resembled the methylation pattern of low-grade lesions for CADM1." (PMID 37047452, 2023). "CADM1 methylation was detected in 18/24 (75%) of the cervical cancer plasma samples, MAL methylation in 10/24 (41.7%), and CADM1/MAL methylation in 20/24 (83.3%) of the samples." (PMID 36010947, 2022). "They found that in tissue the CADM1/MAL combination was superior to discriminate each, CIN3 and cervical cancer from normal tissue/CIN1 with methylation-positivity rates of 97% (CIN3) and 99% (cervical cancer)." (PMID 35725812, 2022). "With detection limits down to 0.1% (CADM1) and 0.2% (MAL), these markers have the potential to serve as sensitive additional and easily applicable tools in cervical cancer management." (PMID 36010947, 2022). "Our data further confirm the possible role of promoter methylation of RARB, CADM1, DAPK1, and PAX1 in cervical cancer tumorigenesis." (PMID 33718129, 2021). "This section describes the usefulness of CADM1 as a biomarker to evaluate the disease progression and severity in several diseases, such as ATLL, cervical cancer, and chronic kidney disease." (PMID 33419290, 2020). "This study aimed to evaluate the performance of methylation status of three tumor suppressor genes (CADM1, FAM19A4, and MAL) and HPV genotyping in detection of cytologic and histologic abnormalities in cervical cancer screening." (PMID 30608989, 2019). "Although sample sizes were limited, CADM1/MAL/miR124-2 methylation was strongly related to the severity of cervical disease and was always positive in cervical cancer." (PMID 29069800, 2017). "Previous data related to cervical cancer showed that DAPK1, FHIT, MGMT, CDKN2A, CADM1 and MAL were frequently methylated genes in cervical carcinogenesis." (PMID 25845528, 2015). "The high frequencies of hypermethylation in RARB (40% vs. 38%), CADM1 (50% vs. 44%), and DAPK1 (33% vs. 19%) were shared between HPV-positive OPSCC and cervical cancer." (PMID 25065733, 2014). "Moreover, we found that cervical cancer stage was influenced by RARB (χ2= 7.32; P = 0.002) and CADM1 (χ2=12.68; P = 0.013) hypermethylation, and HIV status (χ2= 19.93; P = 0.001)." (PMID 33718129, 2021).